FGFR1 (fibroblast growth factor receptor 1)
Diseases named in the same sentence as FGFR1 in open-access papers (continued):
Sharing a sentence is not in itself a finding about the gene and the disease.
prostate carcinoma (continued). "FGF23 expression is enhanced in patients with castration-resistant prostate cancer, as well as FGF23/FGFR1/KL in different prostate cancer cell lines." (PMID 33520985, 2020). "The POU1F1-derived tumors have 499 exclusive proteins that participate in events such as Platinum drug resistance (AKT3, BCL2 and GSTT2) and Prostate cancer (FGFR1, IGF1R and PDGFD) among others." (PMID 33261069, 2020). "Type 1 fibroblast growth factor receptor binding (FGFR1) was an important factor in tumor initiation and progression in prostate cancer." (PMID 30867653, 2019). "Differential signaling of FGFR1 and FGFR2 has previously been investigated in mammary epithelial cells and prostate cancer cells using drug-inducible systems, in which FGFR1 and FGFR2 can be expressed and activated at the same level." (PMID 23185502, 2012). "In prostate cancer cells, FGFR1 and FGF2 have recently been reported to be post-transcriptionally repressed by the microRNAs miR15 and miR16." (PMID 23185502, 2012). "In prostate cancer, FGFR1 and FGFR4 as well as the ligands FGF-1, FGF-2, FGF-6, FGF-8, FGF-9, and FGF-17 are all known to be over-expressed." (PMID 22078327, 2011). "Previous work from our group and that of others have further shown that prostate cancer cells have preferential over-expression of FGFR1 and 4 while FGFR2 and 3 are unaltered or down-regulated." (PMID 22078327, 2011). "Some of these genes have known functions in prostate cancer, such as FGFR1, BCL2, HOXC5, HOXA4, TWIST1, EZH2, KLF4, CTGF." (PMID 19262738, 2009). "The case of FGFR1 in prostate cancer is rather clear and our results are in perfect agreement with previous data." (PMID 17137506, 2006). "FGFR1, TACC1 and WT1 gene expression levels were associated with the androgen-independent stage in xenografts and human prostate carcinoma samples." (PMID 17137506, 2006). "In a subset of prostate cancers, however, these authors observed overexpression of both FGFR-1 and FGFR-2 in the epithelial cells, which correlated with poor differentiation." (PMID 12087465, 2002). "To investigate whether and how TME signaling is attributed to FGFR1 overactivation, we performed single-cell RNA-Seq (scRNA-Seq) to analyze the crosstalk between prostate cancer cells and other types of cells in the microenvironment." (PMID 38781024, 2024). "As prostate cancer progresses and differentiation decreases, FGFR1 expression increases." (PMID 38077251, 2023). "Therefore, in mouse models of prostate cancer cells, chemically induced FGFR1 dimerization/activation leads to rapid tumor growth, while inducible FGFR2 expression slows down tumor growth." (PMID 38077251, 2023). "FGFR1 overexpression has also been reported in prostate cancer (PCa), but the underlining mechanisms are not clear." (PMID 37993879, 2023). "CYP2E1 is involved in xenobiotic detoxification but is also a driver of ROS production; FGFR1 is linked to proliferation and treatment resistance; and GSTM2 has been identified in antioxidant defense and has been associated with resilience to treatment and OS-induced stress in prostate cancer." (PMID 41009689, 2025). "GREM1 was reported to bind to the fibroblast growth factor receptor 1 (FGFR1), activating MEK/ERK signaling and driving castration-resistant prostate cancer growth." (PMID 41033552, 2025). "High frequencies of CNAs were observed in PIK3CA, FGFR1, and EGFR in breast, ovary, pancreas, and prostate cancer samples." (PMID 38674331, 2024). "Aberrant activation of the FGFR1 signaling pathway is sufficient to enhance the Warburg effect through differential regulation of LDHA and LDHB in prostate cancer." (PMID 33390837, 2021). "The overall goal of this study was to elucidate the role of FGFR1 induction in acquired resistance to MET and VEGFR2 inhibition by cabozantinib in prostate cancer (PCa) and leverage this understanding to improve therapy outcomes." (PMID 31963871, 2020).
prostate carcinoma (continued). "Similar to these observations based on prostate cancer, mesenchymal-like OSCC cells also produced soluble factors that activate FGFR1(IIIc)." (PMID 31682640, 2019). "In contrast to the consistent reports of FGFR1 as an oncogene, the connection between FGFR2 and prostate cancer progression still remains controversial." (PMID 30837551, 2019). "UCA1 increases cell proliferation through KLF4-KRT6/13 signaling pathway and FGFR1/ERK signaling pathway, respectively, in prostate cancer and hepatocellular carcinoma." (PMID 27713161, 2017). "Using three methods of analysis (DNA microarrays, TMA, and RT-PCR), we have shown that FGFR1, TACC1 and WT1 have much higher levels of expression in human prostate carcinoma than in benign prostate tissue samples, at both mRNA and protein levels." (PMID 17137506, 2006). "In the same way, we observed that the corresponding mRNAs – FGFR1, TACC1, and WT1 on the one hand, and MART1 on the other hand – are overexpressed in HR and HS stage LuCaP 23.1 prostate carcinoma, respectively." (PMID 17137506, 2006). "In this study, we identified four candidate genes – FGFR1, MART1, TACC1 and WT1 – by gene expression profiling of different stages of prostate carcinoma in an animal model." (PMID 17137506, 2006). "We then assessed the expression of four candidate proteins – FGFR1, MART1, TACC1 and WT1 – in human prostate carcinoma samples by IHC." (PMID 17137506, 2006). "We found that expression of FGFR1, WT1, and, to a lesser extent, TACC1 protein is upregulated in advanced stages (pT3 and/or N1/M1) of prostate cancer, whereas MART1 is mainly expressed in localized (pT2) stage prostate cancer." (PMID 17137506, 2006). "Of the four FGFRs, expression of FGFR1 and FGFR2 has been examined in resected prostate cancer specimens." (PMID 15655558, 2005). "FGFR1 is overexpressed in prostate cancer, and FGFR2 has been detected in both prostate cancer and benign prostatic hyperplasia." (PMID 15655558, 2005). "The prostate is known to express FGFR1, 2 and 3, while FGFR4 has only been detected at low levels in prostate cancer cell lines." (PMID 12778074, 2003). "Stigmasterol, isoboldine, and β-sitosterol could target key prostate cancer-related hub genes (e.g., SRC, FGFR1, HSP90AA1); stigmasterol showed the strongest binding to HSP90AA1, and pathway analysis highlighted involvement of PI3K/AKT signaling." (PMID 41158126, 2025). "Furthermore, in prostate cancer, downregulation of miR-15/16 in CAFs relieves repression of the FGF2/FGFR1 axis, further promoting tumor growth and metastasis, highlighting the molecular complexity of CAF–tumor cell interactions." (PMID 41514604, 2025). "We also tested the activation effects of FGF9 on FGFR1 signaling in prostate cancer cells with or without the KLF5KR mutant." (PMID 38781024, 2024). "Moreover, activation of FGFR1, also expressed in the EV-mRNA mPC sample, was described as an important factor to initiate carcinogenesis and EMT in prostate cancer." (PMID 36830940, 2023). "Our study indicated that the protein expression of three markers (FGFR1, LDHB, and MYPT1) were correlated with prostate cancer patients' outcomes (biochemical recurrence) in tumor-adjacent stroma, and such correlations were surprisingly opposite to those in tumor tissues." (PMID 31316912, 2019). "As an example, FGFR1 activation promotes EMT in rodent models of breast and prostate cancer." (PMID 26811493, 2016). "Experimental studies in PCa models showed that one notable function of CRIPTO expression in prostate carcinoma cells may be to augment PI3K/AKT and FGFR1 signaling, which promotes epithelial-mesenchymal transition and sustains a mesenchymal state." (PMID 25596738, 2015). "In prostate cancer, activation of FGFR1 can mediate EMT, raising the question whether FGFR1 signalling may play a different role in invasive compared to non-invasive bladder tumours." (PMID 22701738, 2012). "Expression of FGFR1, MART1, TACC1 and WT1 proteins in human prostate cancer." (PMID 17137506, 2006).
prostate carcinoma (continued). "We have also found that FGFR1 and WT1 mRNA are preferentially expressed in pT3 and/or N1/M1 carcinoma samples, and that MART1 expression is correlated with HS stage LuCaP 23.1 carcinoma and pT2 prostate carcinoma." (PMID 17137506, 2006). "However, neither FGFR1 nor FGFR2 expression in prostate cancer was noted to have any significant correlation to clinical parameters including tumour grade, stage, and outcome on disease survival." (PMID 15655558, 2005).
lymphoid neoplasm (60 papers, 2009 to 2025). A neoplasm composed of a lymphocytic cell population which is usually malignant (clonal) by molecular genetic and/or immunophenotypic analysis. "Myeloid/lymphoid neoplasms with tyrosine kinase gene fusions, including FGFR1 rearrangement, which are typically associated with eosinophilia, can present as acute leukemia with blasts showing a mixed phenotype, meeting the MPAL lineage assignment criteria." (PMID 40075717, 2025). "The PCM1 gene as partner in the chimera PCM1::JAK2 has been implicated in the pathogenesis of also other acute myeloid/lymphoid neoplasms whereas rearrangements of FGFR1 are rare." (PMID 38571499, 2024). "Myeloid and lymphoid neoplasms associated with FGFR1 abnormalities (MLN-FGFR1 abnormalities) are rare hematologic malignancies associated with chromosome 8p11.2 abnormalities." (PMID 38457113, 2024). "Type I FGFR1 fusions are associated with “myeloid/lymphoid neoplasms with FGFR1 rearrangement”, an extremely rare myeloproliferative disorder characterised by the presence of FGFR1 rearrangement." (PMID 37130917, 2023). "In a case series where 22 patients diagnosed with myeloid/lymphoid neoplasm associated with eosinophilia and FGFR1 rearrangements were treated with allogeneic hematopoietic stem cell transplantation, 7 of them had BCR::FGFR1 rearrangement." (PMID 36698221, 2023). "In this case, PET/CT imaging played a crucial role in accurately diagnosing a myeloid/lymphoid neoplasm with FGFR1 rearrangement, a condition associated with a poor prognosis, enabling the patient to undergo allogeneic transplantation." (PMID 38024625, 2023). "Hematopoietic neoplasms associated with FGFR1 rearrangement are included in the family of myeloid and lymphoid neoplasms with varying responsiveness to TKIs, though other neoplasms such as AMLs, ALLs, and MPSs with FGFR3 are characterized by aggressive clinical behavior and resistance to imatinib." (PMID 36551764, 2022). "For this reason, the 2008 WHO Classification of hematopietic and lymphoid tumors has introduced a separate diagnostic category for such disorders, referred to as “Myeloid and Lymphoid Neoplasms with Eosinophilia and Abnormalities of PDGFRα, PDGFRβ or FGFR1”." (PMID 26943776, 2016). "Several case reports and studies have highlighted the critical role of FGFR1 in the development of myeloid and lymphoid neoplasms." (PMID 41180818, 2025). "Among them, pemigatinib, a reversible ATP-competitive FGFR inhibitor, has been recently approved as a novel drug for treatment of myeloid/lymphoid neoplasms with FGFR1 rearrangement in the US and Japan." (PMID 38457113, 2024). "Cases of AML with PDGFRA, PDGFRΒ, and FGFR1 rearrangements are included in the current WHO classification in the broad category of “myeloid/lymphoid neoplasms with eosinophilia and tyrosine kinase gene fusions”." (PMID 38337573, 2024). "Pemigatinib is also approved for relapsed or refractory myeloid/lymphoid neoplasms with FGFR1 gene rearrangement." (PMID 39886662, 2024). "Recently, pemigatinib, an FGFR2 inhibitor used in patients with FGFR2-rearranged cholangiocarcinoma, received FDA approval for relapsed/refractory myeloid and/or lymphoid neoplasms with FGFR1 rearrangements." (PMID 38337573, 2024). "EMS was categorized as myeloid/lymphoid neoplasms with FGFR1 rearrangement in the 2017 revision of the World Health Organization classification of myeloid neoplasms and acute leukemia." (PMID 36930401, 2023). "Based on these findings, the patient was diagnosed with myeloid/lymphoid neoplasm with FGFR1 rearrangement." (PMID 38024625, 2023). "The myeloid/lymphoid neoplasms with eosinophilia and FGFR1 rearrangements are a provisional entity according to 2016 WHO classification, defined as a heterogeneous neoplasm, consequence of multiple translocations with a breaking point 8p11." (PMID 36698221, 2023).
lymphoid neoplasm (continued). "In 2020, pemigatinib was approved by the FDA as the first targeted therapy in advanced cholangiocarcinoma and in August 2022 as a treatment for relapsed or refractory myeloid/lymphoid neoplasms (MLNs) with FGFR1 rearrangement." (PMID 37715207, 2023). "As for hematological malignancies, the FGFR1/2/3 inhibitor pemigatinib has shown impressive efficacy in a small registration-directed trial in patients with FGFR1-rearranged myeloid/lymphoid neoplasms." (PMID 36551764, 2022). "ZMYM2 has also been implicated in cancer as a fusion protein with the Fibroblast growth factor receptor 1 (FGFR1) in 8p11 myeloproliferative syndrome (EMS), where it constitutes ∼ 50% of all cases of FGFR1-fusion related myeloid/lymphoid neoplasms." (PMID 35253893, 2022). "There is also an ongoing trial on the use of another FGFR inhibitor, pemigatinib (INCB054828) in patients with myeloid/lymphoid neoplasms with FGFR1 rearrangement (ClinicalTrials.gov identifier: NCT03011372)." (PMID 36077521, 2022). "Pemigatinib: INCB054828 is an oral FGFR1, 2 and 3 inhibitor that is currently under evaluation in FGFR1-rearranged myeloid/lymphoid neoplasms." (PMID 33418988, 2021). "The current 2017 WHO classification recognizes the following specific diseases: M/LNs-Eo with rearrangements of PDGFRA, PDGFRB and FGFR1 respectively and the provisional entity of myeloid/lymphoid neoplasms with PCM1-JAK2 rearrangement." (PMID 34205834, 2021). "It consists of a distinct disease from myeloid/lymphoid neoplasms associated with eosinophilia and rearrangement of PDGFRA, PDGFRB, or FGFR1, or with PCM1-JAK2." (PMID 34441019, 2021). "In 2016, the World Health Organization (WHO) classified EMS as a myeloid/lymphoid neoplasm associated with eosinophilia, and the genes most commonly rearranged in these neoplasm include PDGFRA, PDGFRB, PCM1-JAK2, and FGFR1." (PMID 31980503, 2020). "This Phase 2 Open Label study aims to evaluate the effectiveness of the FGFR1-3 kinase inhibitor pemigatinib (INCB054828) in patients with myeloid or lymphoid neoplasm with FGFR fusions." (PMID 31980503, 2020). "A distinct classification of myeloid and lymphoid neoplasms associated with eosinophilia and rearrangements of PDGFRA, PDGFRB, FGFR1 or with a PCM1-JAK2 rearrangement is described in the WHO 2017." (PMID 30696948, 2019). "The category of myeloid/lymphoid neoplasms with eosinophilia and rearrangement of PDGFRA, PDGFRB, FGFR1 and PCM1-JAK2 represents an uncommon cause of eosinophilic lung infiltrate." (PMID 31744552, 2019). "As the spectrum of malignancies associated with this rearrangement expanded, the 2008 WHO classification developed a category for these neoplasms, “Myeloid and lymphoid neoplasms associated with eosinophilia and abnormalities of PDGFRA, PDGFRB, or FGFR1 ”." (PMID 26457233, 2015). "Because FGFR inhibitors may be used as first-line therapy for patients with myeloid/lymphoid neoplasms with FGFR1 rearrangement, gene-level diagnosis testing for such aberrations is clinically important." (PMID 38571499, 2024). "In the 5th WHO classification of hematopoietic and lymphoid neoplasms, it was classified as “myeloid and lymphoid neoplasms associated with FGFR1 abnormalities (MLN-FGFR1 abnormalities)” in the “myeloid and lymphoid neoplasms with eosinophilia and tyrosine kinase gene fusions (MLN-TK)”." (PMID 38457113, 2024). "This category name has changed from the previous “myeloid/lymphoid neoplasms with eosinophilia and rearrangement of PDGFRA, PDGFRB or FGFR1, or with PCM1::JAK2” (MLN-eo), to specify the underlying molecular genetic changes and to include cases with ETV6::ABL1, FLT3 fusions or other TK fusion genes." (PMID 37454239, 2023). "In August 2022, the US FDA approved pemigatinib for treatment of relapsed or refractory myeloid/lymphoid neoplasms with FGFR1 rearrangement, based on the results of phase 2-FIGHT-203 Study (NCT03011372) that show a complete response of 75.8% in previously treated patients." (PMID 38098111, 2023).